OPRM1 (opioid receptor mu 1)
Description:
Receptor for endogenous opioids such as beta-endorphin and endomorphin. Receptor for natural and synthetic opioids including morphine, heroin, DAMGO, fentanyl, etorphine, buprenorphin and methadone. Also activated by enkephalin peptides, such as Met-enkephalin or Met-enkephalin-Arg-Phe, with higher affinity for Met-enkephalin-Arg-Phe (By similarity). Agonist binding to the receptor induces coupling to an inactive GDP-bound heterotrimeric G protein complex and subsequent exchange of GDP for GTP in the G protein alpha subunit leading to dissociation of the G protein complex with the free GTP-bound G protein alpha and the G protein beta-gamma dimer activating downstream cellular effectors. The agonist- and cell type-specific activity is predominantly coupled to pertussis toxin-sensitive G(i) and G(o) G alpha proteins, GNAI1, GNAI2, GNAI3 and GNAO1 isoforms Alpha-1 and Alpha-2, and to a lesser extent to pertussis toxin-insensitive G alpha proteins GNAZ and GNA15. They mediate an array of downstream cellular responses, including inhibition of adenylate cyclase activity and both N-type and L-type calcium channels, activation of inward rectifying potassium channels, mitogen-activated protein kinase (MAPK), phospholipase C (PLC), phosphoinositide/protein kinase (PKC), phosphoinositide 3-kinase (PI3K) and regulation of NF-kappa-B (By similarity). Also couples to adenylate cyclase stimulatory G alpha proteins (By similarity). The selective temporal coupling to G proteins and subsequent signaling can be regulated by RGSZ proteins, such as RGS9, RGS17 and RGS4 (By similarity). Phosphorylation by members of the GPRK subfamily of Ser/Thr protein kinases and association with beta-arrestins is involved in short-term receptor desensitization (By similarity). Beta-arrestins associate with the GPRK-phosphorylated receptor and uncouple it from the G protein thus terminating signal transduction (By similarity). The phosphorylated receptor is internalized through endocytosis via clathrin-coated pits which involves beta-arrestins (By similarity). The activation of the ERK pathway occurs either in a G protein-dependent or a beta-arrestin-dependent manner and is regulated by agonist-specific receptor phosphorylation (By similarity). Acts as a class A G protein-coupled receptor (GPCR) which dissociates from beta-arrestin at or near the plasma membrane and undergoes rapid recycling (By similarity). Receptor down-regulation pathways are varying with the agonist and occur dependent or independent of G protein coupling (By similarity). Endogenous ligands induce rapid desensitization, endocytosis and recycling (By similarity). Heterooligomerization with other GPCRs can modulate agonist binding, signaling and trafficking properties (By similarity). [Isoform 12]: Couples to GNAS and is proposed to be involved in excitatory effects. [Isoform 16]: Does not bind agonists but may act through oligomerization with binding-competent OPRM1 isoforms and reduce their ligand binding activity. [Isoform 17]: Does not bind agonists but may act through oligomerization with binding-competent OPRM1 isoforms and reduce their ligand binding activity.
Synonyms: M-OR-1; MOP; MOR1; LMOR; MOR; OPRM
Tractability: Small molecule: an approved drug acts on it; a structure with a bound ligand is known; a high-quality ligand is known; it belongs to a druggable protein family. Antibody: UniProt places it where antibodies can reach, with high confidence; its Gene Ontology location is reachable by antibodies, with high confidence; UniProt predicts a signal peptide or a membrane-spanning region. PROTAC: UniProt records ubiquitination sites on it; a small molecule that binds it is known. Other modalities: a drug acting on it is in phase 2 or 3 trials.
Target class: Short peptide receptor (family A GPCR); Family A G protein-coupled receptor; Peptide receptor (family A GPCR); Opioid receptor; Membrane receptor
Chemical probes: CHEMBL3216999, ENDOMORPHIN 2, O-DESMETHYL TRAMADOL, OLICERIDINE
Safety:
Unwanted effects reported when the protein is acted on. In parentheses: how it was acted on, where the effect was seen, and who reports it.
dyspepsia (Lynch et al. (2017): inhibition, acute dosing, pancreas, nervous system, respiratory, renal, cardiovascular, gastrointestinal; Bowes et al. (2012): inhibition, cardiovascular system, central nervous system, gastrointestinal)
respiratory depression (Bowes et al. (2012): activation, cardiovascular system, central nervous system, gastrointestinal; ClinPGx)
sedation (Bowes et al. (2012): activation, cardiovascular system, central nervous system, gastrointestinal; Lynch et al. (2017): activation, acute dosing, pancreas, nervous system, respiratory, renal, cardiovascular, gastrointestinal)
abuse liability (activation; cardiovascular system, central nervous system, gastrointestinal; source: Bowes et al. (2012))
decreased anxiety (activation, acute dosing; pancreas, nervous system, respiratory, renal, cardiovascular, gastrointestinal; source: Lynch et al. (2017))
decreased cardiac output (activation, acute dosing; pancreas, nervous system, respiratory, renal, cardiovascular, gastrointestinal; source: Lynch et al. (2017))
decreased gastric acid secretion (activation, acute dosing; pancreas, nervous system, respiratory, renal, cardiovascular, gastrointestinal; source: Lynch et al. (2017))
decreased gastric emptying (inhibition, acute dosing and activation, acute dosing; pancreas, nervous system, respiratory, renal, cardiovascular, gastrointestinal; source: Lynch et al. (2017))
decreased gastrointestinal motility (activation; cardiovascular system, central nervous system, gastrointestinal; source: Bowes et al. (2012))
decreased gastrointestinal transit (activation, acute dosing; pancreas, nervous system, respiratory, renal, cardiovascular, gastrointestinal; source: Lynch et al. (2017))
decreased heart rate (activation, acute dosing; pancreas, nervous system, respiratory, renal, cardiovascular, gastrointestinal; source: Lynch et al. (2017))
decreased pain (activation, acute dosing; pancreas, nervous system, respiratory, renal, cardiovascular, gastrointestinal; source: Lynch et al. (2017))
decreased respiratory rate (activation, acute dosing; pancreas, nervous system, respiratory, renal, cardiovascular, gastrointestinal; source: Lynch et al. (2017))
decreased/increased blood pressure (activation, acute dosing; pancreas, nervous system, respiratory, renal, cardiovascular, gastrointestinal; source: Lynch et al. (2017))
decreased/increased body temperature (activation, acute dosing; pancreas, nervous system, respiratory, renal, cardiovascular, gastrointestinal; source: Lynch et al. (2017))
decreased/increased convulsions (activation, acute dosing; pancreas, nervous system, respiratory, renal, cardiovascular, gastrointestinal; source: Lynch et al. (2017))
decreased/increased pupil diameter (activation, acute dosing; pancreas, nervous system, respiratory, renal, cardiovascular, gastrointestinal; source: Lynch et al. (2017))
drug abuse/dependence (activation, acute dosing; pancreas, nervous system, respiratory, renal, cardiovascular, gastrointestinal; source: Lynch et al. (2017))
flatulence (inhibition; cardiovascular system, central nervous system, gastrointestinal; source: Bowes et al. (2012))
gas (inhibition, acute dosing; pancreas, nervous system, respiratory, renal, cardiovascular, gastrointestinal; source: Lynch et al. (2017))
hypothermia (activation; cardiovascular system, central nervous system, gastrointestinal; source: Bowes et al. (2012))
increased blood glucose (activation, acute dosing; pancreas, nervous system, respiratory, renal, cardiovascular, gastrointestinal; source: Lynch et al. (2017))
increased blood insulin (activation, acute dosing; pancreas, nervous system, respiratory, renal, cardiovascular, gastrointestinal; source: Lynch et al. (2017))
increased blood pressure (inhibition, acute dosing; pancreas, nervous system, respiratory, renal, cardiovascular, gastrointestinal; source: Lynch et al. (2017))
increased gastrointestinal motility (inhibition; cardiovascular system, central nervous system, gastrointestinal; source: Bowes et al. (2012))
increased gastrointestinal transit (inhibition, acute dosing; pancreas, nervous system, respiratory, renal, cardiovascular, gastrointestinal; source: Lynch et al. (2017))
increased heart rate (inhibition, acute dosing; pancreas, nervous system, respiratory, renal, cardiovascular, gastrointestinal; source: Lynch et al. (2017))
increased urinary sodium excretion (activation, acute dosing; pancreas, nervous system, respiratory, renal, cardiovascular, gastrointestinal; source: Lynch et al. (2017))
increased urine excretion (activation, acute dosing; pancreas, nervous system, respiratory, renal, cardiovascular, gastrointestinal; source: Lynch et al. (2017))
increased/decreased convulsions (inhibition, acute dosing; pancreas, nervous system, respiratory, renal, cardiovascular, gastrointestinal; source: Lynch et al. (2017))
and 43 more effects
Gene: Protein-coding gene on chromosome 6 (154,010,496 to 154,246,867, forward strand). Ensembl gene ENSG00000112038.
Subcellular location: Cell membrane; Cell projection, axon; Perikaryon; Cell projection, dendrite; Endosome; Cytoplasm (Isoform 12)
Pathways (Reactome):
Signal Transduction: G alpha (i) signalling events; G-protein activation; Opioid Signalling; Peptide ligand-binding receptors
Immune System: Interleukin-4 and Interleukin-13 signaling
Gene Ontology:
Molecular function: beta-endorphin receptor activity; G-protein alpha-subunit binding; protein binding; G protein-coupled receptor activity; G-protein beta-subunit binding; morphine receptor activity; neuropeptide binding; voltage-gated calcium channel activity; G protein-coupled opioid receptor activity; G protein-coupled peptide receptor activity
Biological process: behavioral response to ethanol; negative regulation of Wnt protein secretion; regulation of cellular response to stress; adenylate cyclase-inhibiting G protein-coupled acetylcholine receptor signaling pathway; G protein-coupled opioid receptor signaling pathway; G protein-coupled receptor signaling pathway, coupled to cyclic nucleotide second messenger; negative regulation of cell population proliferation; neuropeptide signaling pathway; phospholipase C-activating G protein-coupled receptor signaling pathway; positive regulation of ERK1 and ERK2 cascade; positive regulation of neurogenesis; regulation of NMDA receptor activity; sensory perception; sensory perception of pain; calcium ion transmembrane transport; cellular response to morphine; G protein-coupled receptor signaling pathway; presynaptic modulation of chemical synaptic transmission; transmission of nerve impulse
Cellular component: cytoplasm; plasma membrane; axon; dendrite; endoplasmic reticulum; endosome; Golgi apparatus; neuron projection; perikaryon; GABA-ergic synapse; membrane; presynapse
Genetic constraint (gnomAD): Loss-of-function variants: 24 observed, 31.18 expected, observed/expected ratio (o/e) 0.77, 90% interval 0.56 to 1.08. The upper end of that interval is the gene's LOEUF score, 1.08, which puts it in group 4 of 6, group 1 being the genes least tolerant of losing a copy. Missense variants: 533 observed, 530.91 expected, observed/expected ratio (o/e) 1, 90% interval 0.93 to 1.08. Synonymous variants: 195 observed, 198.99 expected, observed/expected ratio (o/e) 0.98, 90% interval 0.87 to 1.1.
Homologues: Orthologues: macaque OPRM1 (98% identical), chimpanzee OPRM1 (97% identical), dog OPRM1 (94% identical), guinea pig OPRM1 (94% identical), rat Oprm1 (93% identical), pig OPRM1 (93% identical), rabbit OPRM1 (93% identical), mouse Oprm1 (92% identical), tropical clawed frog oprm1 (76% identical), zebrafish oprm1 (72% identical), Caenorhabditis elegans trhr-1 (23% identical), Drosophila melanogaster Rh7 (20% identical). Paralogues in human: OPRK1 (56% identical), OPRD1 (55% identical), OPRL1 (46% identical), SSTR1 (33% identical), SSTR2 (33% identical), SSTR5 (32% identical), SSTR4 (31% identical), NPBWR2 (30% identical), SSTR3 (30% identical), NPBWR1 (28% identical), KISS1R (25% identical), CMKLR2 (23% identical), and 5 more.
Diseases named in the same sentence as OPRM1 in open-access papers:
OPRM1 is named in the same sentence as 194 diseases in open-access papers, as found by Europe PMC text mining. Sharing a sentence is not in itself a finding about the gene and the disease. The quoted sentences say what the papers report.
respiratory depression (96 papers, 2008 to 2026). A decrease in ventilation secondary to impaired signals from the central nervous system. "One study demonstrated the role of mu1 opioid receptor 1 (OPRM1) gene variants in morphine-induced respiratory depression (MIRD) in young people following surgery for spine fusion." (PMID 41009999, 2025). "Polymorphisms in the OPRM1 gene, encoding the μ-opioid receptor, have been linked to variability in respiratory depression and opioid sensitivity." (PMID 40649133, 2025). "Using in situ hybridization, we first quantified the expression of Sst (gene encoding somatostatin) and Oprm1 (gene encoding MORs) mRNAs in brainstem regions involved in the control of breathing and respiratory depression." (PMID 37364996, 2023). "We examined the coexpression of Sst (gene encoding somatostatin) and Oprm1 (gene encoding MORs) mRNAs in brainstem regions involved in respiratory depression." (PMID 37364996, 2023). "Both populations of Oprm1+ dorsolateral pontine neurons are also likely involved in opioid-induced respiratory depression." (PMID 37314062, 2023). "In our study, we found co-expression of Oprm1 (the gene coding for MORs) and Tac1 in preBötC neurons, and stimulation of Tac1 preBötC cells entirely reversed respiratory depression by fentanyl." (PMID 37458576, 2023). "The roles of Oprm1 at a discrete region on mu opioid-induced motivation, naloxone aversion, analgesia, respiratory depression, and reward were demonstrated by using this conditional Oprm1 KO mouse." (PMID 35328429, 2022). "Several other GPCRs, including Oprm1 which plays an important role in opioid-induced respiratory depression, are expressed along with Calca, but also in other clusters." (PMID 36317965, 2022). "Our results therefore support the idea that, because of the high expression of Oprm1 in Sst mRNA-expressing cells, these cells may be vulnerable to opioid drugs and contribute to respiratory depression." (PMID 37364996, 2023). "Considering that photostimulation of Tac1 cells increased breathing and that these cells co-expressed Oprm1, we aimed to determine whether stimulation of Tac1-expressing cells can reverse opioid-induced respiratory depression." (PMID 37458576, 2023). "Considering the role of Tac1-expressing cells in rhythmic breathing and knowing that the preBötC plays a major part in respiratory depression by opioid drugs, we determined whether Tac1 mRNA is co-expressed with Oprm1 (gene for MORs) mRNA in the preBötC." (PMID 37458576, 2023). "Also, we do not yet know the ontological relationships of PB neurons expressing Oxtr1 (water intake), Htr2c (food, water, and salt intake), or Oprm1 (opioid‐withdrawal; opioid‐induced respiratory depression) relative to our developmental‐genetic framework." (PMID 35134251, 2022). "In addition, microperfusion of DAMGO close to the preBötC, as identified with Tacr1 expression, elicits a potent and fast respiratory depression, and the region were DAMGO acted also overlapped with Oprm1 and Tacr1-positive neurons." (PMID 37089428, 2023).
depression (46 papers, 2006 to 2026). "In conclusion, the present study suggests that the A118G OPRM1 polymorphism is associated with sociotropy and interpersonal sensitivity, interpersonal vulnerabilities to depression." (PMID 35761357, 2022). "This study suggests that the A118G OPRM1 polymorphism is associated with sociotropy and interpersonal sensitivity, interpersonal vulnerabilities to depression." (PMID 35761357, 2022). "Although the present study aimed at elucidating the associations of the OPRM1 polymorphism with depression vulnerabilities, from a broader perspective it provides further evidence for the implication of MOR in social bonding behaviors." (PMID 35761357, 2022). "We next examined the distribution of genotypes and estimated odds ratio of the studied candidate SNPs of COMT, SNCA9A, and OPRM1 in relation to the risk of depression in our PD patients." (PMID 28740224, 2017). "Similarly, ApoE, activated in Oprm1 positive cells in the striatum during morphine withdrawal, has been implicated in several neuropsychiatric disorders including depression and schizophrenia, which can be co-morbid with substance use disorder." (PMID 36534642, 2022). "BDNF rs6265 was associated with catastrophising (p = 0.044), OPRM1 rs1799971 with anxiety (p = 0.030), and MAOA rs1137070 with depression (p = 0.020)." (PMID 41460692, 2026). "The molecular docking studies have elucidated potential interactions between the compounds of the SPZY formula and its two key targets in FC comorbid with depression, including OPRM1 and SLC6A3." (PMID 40910010, 2025). "Analysis of transcriptomic data from depression-related mouse models in the GEO database enabled the identification of key genes, including Oprm1, BDNF, and Tph2, which exhibited marked expression differences between the NAC and PFC regions." (PMID 40656047, 2025). "OPRM1 is a receptor for endogenous opioids and its activation can lead to feelings of pleasure and euphoria, which are often disrupted in individuals with depression." (PMID 38567354, 2024). "The patients with OUD showed a significant decrease in OPRM1 DNA methylation, which correlated with clinical outcomes like pain relief, depression and different adverse events." (PMID 38949208, 2024). "This low OPRM1 DNA methylation correlated with less pain relief, depression and a different pattern of AEs in cases." (PMID 38949208, 2024). "From the neuroendocrine system, OPRM1 rs1799971 correlated increasing levels of female's Anxiety, depression and Social Dysfunction scores." (PMID 30656852, 2019). "However, the associations between these components and OPRM1, SLC6A3, and their therapeutic mechanisms for treating constipation and depression are reported here for the first time." (PMID 40910010, 2025). "There have also been no genome‐wide association studies focusing on the A118G OPRM1 polymorphism or the SNPs around this polymorphism in relation to personality traits or major depression, to our knowledge." (PMID 35761357, 2022). "In contrast with OPRM1, variants in PPP6C have been associated with numerous brain- and SUD-related phenotypes, notably opioid medication use, alcohol consumption, numerous smoking phenotypes, and depression among others." (PMID 36207451, 2022). "Bivariate analyses taking HADS-A or HADS-D scores as dependent variables showed that the intake of fosaprepitant (compared to not) and having the OPRM1 AG genotype compared to AA were significantly associated with lower depression." (PMID 34330229, 2021). "Our study demonstrates that OPRM1 G allele carriers show aberrant reward responding, similar to that observed with reduced phasic dopamine signaling, rather than that seen in individuals with clinical depression." (PMID 21912675, 2011). "Genes like Oprm1 and BDNF, which exhibited significant differential expression and strong functional relevance in the neurobiology of depression, emerged as potential molecular indicators." (PMID 40656047, 2025).